SSTR5 (somatostatin receptor 5)
Description:
Receptor for somatostatin 28 and to a lesser extent for somatostatin-14. The activity of this receptor is mediated by G proteins which inhibit adenylyl cyclase. Increases cell growth inhibition activity of SSTR2 following heterodimerization.
Synonyms: SS-5-R; SST5
Tractability: Small molecule: a high-quality ligand is known; it belongs to a druggable protein family. Antibody: its Gene Ontology location is reachable by antibodies, with high confidence; UniProt places it where antibodies can reach, with medium confidence; UniProt predicts a signal peptide or a membrane-spanning region; the Human Protein Atlas places it where antibodies can reach. PROTAC: ubiquitination databases record sites on it; a small molecule that binds it is known. Other modalities: an approved drug acts on it.
Target class: Peptide receptor (family A GPCR); Membrane receptor; Short peptide receptor (family A GPCR); Family A G protein-coupled receptor; Somatostatin receptor
Chemical probes: CHEMBL1080585, CHEMBL236788 (high quality)
Gene: Protein-coding gene on chromosome 16 (1,063,867 to 1,081,467, forward strand). Ensembl gene ENSG00000162009.
Subcellular location: Cell membrane
Subcellular location (Human Protein Atlas): Plasma membrane
Pathways (Reactome):
Signal Transduction: G alpha (i) signalling events; Peptide ligand-binding receptors
Gene Ontology:
Molecular function: protein binding; neuropeptide binding; somatostatin receptor activity; G protein-coupled receptor activity
Biological process: positive regulation of cytokinesis; cellular response to glucocorticoid stimulus; G protein-coupled receptor signaling pathway; G protein-coupled receptor signaling pathway, coupled to cyclic nucleotide second messenger; negative regulation of cell population proliferation; neuropeptide signaling pathway; regulation of insulin secretion; somatostatin signaling pathway
Cellular component: plasma membrane; neuron projection; membrane
Genetic constraint (gnomAD): Loss-of-function variants: 1 observed, 0.44 expected, observed/expected ratio (o/e) 2.3. That is too few expected variants to judge how well the gene tolerates losing a copy. Missense variants: 443 observed, 478.34 expected, observed/expected ratio (o/e) 0.93, 90% interval 0.86 to 1. Synonymous variants: 222 observed, 227.43 expected, observed/expected ratio (o/e) 0.98, 90% interval 0.87 to 1.09.
Homologues: Orthologues: macaque SSTR5 (97% identical), dog SSTR5 (83% identical), rat Sstr5 (80% identical), mouse Sstr5 (80% identical), pig SSTR5 (80% identical), guinea pig SSTR5 (78% identical), chimpanzee SSTR5 (63% identical), zebrafish si:zfos-169g10.2 (53% identical), zebrafish sstr3 (51% identical), Drosophila melanogaster Rh7 (23% identical), Caenorhabditis elegans trhr-1 (23% identical). Paralogues in human: SSTR3 (53% identical), SSTR2 (50% identical), SSTR4 (48% identical), SSTR1 (46% identical), NPBWR2 (37% identical), OPRD1 (37% identical), OPRL1 (36% identical), OPRM1 (35% identical), OPRK1 (32% identical), NPBWR1 (32% identical), KISS1R (30% identical), CMKLR2 (26% identical), and 5 more.
Diseases named in the same sentence as SSTR5 in open-access papers:
SSTR5 is named in the same sentence as 94 diseases in open-access papers, as found by Europe PMC text mining. Sharing a sentence is not in itself a finding about the gene and the disease. The quoted sentences say what the papers report.
pituitary tumor (23 papers, 2013 to 2025). A benign or malignant neoplasm affecting the pituitary gland. "Regarding SSTR5 gene, it has been found that T allele of rs34037914 single nucleotide polymorphism predisposes to resistance to antiproliferative effects of SS, increased aggressiveness, and post-surgical reoccurrence of pituitary tumors." (PMID 26733942, 2015). "Nevertheless, our correlation analyses of natriuretic peptide gene expression in feline pituitary tumour samples reveal relationships between the different peptides and their receptors, as well as genes encoding physiological regulators of somatotrope function (D2R, SSTR5, and GHR)." (PMID 33499110, 2021). "Adrenocorticotropic hormone (ACTH)-secreting pituitary tumors mainly express somatostatin receptor 5 (SSTR5) since SSTR2 is downregulated by the elevated levels of glucocorticoids that characterize patients with Cushing’s disease (CD)." (PMID 37435448, 2022). "SSTR5 is the molecular target of pasireotide, the only approved pituitary tumor-targeted drug for the treatment of CD." (PMID 37435448, 2022). "NPPC expression was negatively correlated with pituitary tumour volume and SSTR5 expression, but positively correlated with D2R and GHR expression." (PMID 33499110, 2021). "SSTR5 and other SSTRs are widely and variably expressed in a variety of tumors such as gastroenteropancreatic tumors, pituitary tumors, and carcinoid tumors." (PMID 25009500, 2014). "Synthetic therapeutic agonists showing selectivity for SSTR2 (Octreotide) or for SSTR2 and SSTR5 (Pasireotide) have been approved for the treatment of patients with acromegaly and Cushing’s syndrome, as their pituitary tumors highly express SSTR2 or SSTR2/SSTR5, respectively." (PMID 37444563, 2023). "Both DRD2 and SSTR5 are also involved in ACTH release in pituitary tumors." (PMID 27856505, 2017). "While several studies have suggested a strong SSTR5 IHC expression might be linked to SG tumors and responsiveness to Pasireotide in GH-secreting pituitary tumors, the data regarding the predictive role of SSTR5 IHC expression in corticotropinomas are less clear." (PMID 40364036, 2025). "In fact, in vivo pituitary tumors expressing low levels of SSTR2 and high levels of SSTR5 showed a greater therapeutic response with the use of pasireotide versus octreotide." (PMID 39064468, 2024). "SSAs stimulate p27 expression and inhibit the MAPK pathway in pituitary tumors by binding to SSRT2 and SSRT5.Studies have found that SSTR2 and SSTR5 also express in TSHoma cells, suggesting that SSAs can be used to treat TSHoma." (PMID 37587420, 2023). "Its high affinity for the somatostatin receptor subtype 5 (SSTR5), abundantly expressed in ACTH-secreting pituitary tumors, results in ACTH and consequently cortisol inhibition." (PMID 31313243, 2020). "To analyze whether all interaction partners are present in tissues expressing the SSTR5, we compared expression patterns in brain, pituitary and in two cells lines which are known to express the SSTR5, the pancreatic Min-6 line and the mouse pituitary tumour line AtT-20." (PMID 24523912, 2014). "Interestingly, pasireotide treatment increased SSTR5 expression in BON‐1 cells, similar to that previously reported by our group in pituitary tumor cells." (PMID 34601790, 2022).
adenoma (21 papers, 2013 to 2026). A neoplasm arising from the epithelium. "Moreover, USP8-mutated adenomas were more likely to express SSTR5." (PMID 38862897, 2024). "Furthermore, somatostatin receptor 5 (SSRT5) was more frequent in USP8-mutated adenomas." (PMID 38862897, 2024). "Overexpression of SSTR5 has recently been reported among USP8-mutated corticotrope adenomas compared to wild-type adenomas; however, USP8 mutations were found in adenomas from female patients only, thus this finding could be gender- rather than USP8-variant specific." (PMID 32183012, 2020). "In comparison, SSTR5 signal was high in 26 out of 43 samples, while seven adenomas showed a moderate and six cases a low expression rate of SSTR5." (PMID 34674191, 2022). "In comparison, 26 out of 43 adenomas showed more than 50% positive-stained cells (high expression) regarding SSTR5, while seven samples showed moderate and six a low expression rate." (PMID 34674191, 2022). "The mean ID score of nonadenomatous samples was significantly higher for SSTR2A and SSTR5 (p = 0.0126 and 0.0008, respectively) than that of adenoma samples." (PMID 30627156, 2018). "In order to detect the expression pattern of SSTR2 and SSTR5 in the normal pituitary and adenomas from both the DS group and SA group, we performed IHC analysis by using rabbit monoclonal antibodies against these two receptors." (PMID 28396686, 2017). "IHC analysis, using a 12-grade scoring system, with rabbit monoclonal antibodies against SSTR2 and SSTR5, was performed on all adenoma tissues." (PMID 28396686, 2017). "Both SSTR2 and SSTR5 were significantly elevated in TSHoma compared to other adenomas." (PMID 39202532, 2024). "An increased expression of somatostatin receptor SSTR5 has also been reported in a transcriptome analysis via the RNA sequencing of human ACTH-secreting adenoma cells, with potential therapeutic implications (i.e., possible different sensitivity to pasireotide)." (PMID 35743266, 2022). "Even though HTL0030310 structure is still undisclosed, Sosei Heptares designed this peptide as a selective SSTR5 (somatostatin 5) receptor agonist to treat endocrine disorders modulating the excess release of hormones from adenomas (benign tumors) of the pituitary gland." (PMID 34195230, 2021). "Overall, 233 adenoma cases were available for SSTR5 expression analysis." (PMID 30627156, 2018). "In Cushing's disease, ACTH secreting adenomas predominantly express SSTR5 but SSTR2 expression is also seen, which may be involved in the hypercortisolaemia seen in our case." (PMID 24616766, 2013). "In addition to the expression of SSTR2 mRNA, the expression of SSTR5 mRNA may also influence tumor shrinkage by somatostatin analogs against TSH-secreting adenomas." (PMID 39202532, 2024). "Furthermore, a low level or no expression of SSTR5 was mostly associated with adenoma size smaller than 1 cm (70%, 7/10)." (PMID 34674191, 2022). "In the three prolactin-secreting adenomas studied, the expression of SSTR2 was stronger than that of SSTR5." (PMID 39202532, 2024). "In 1994, Greenman and Melmed analyzed SSTR 3, SSTR4, and SSTR5 in 33 pituitary adenomas and SSTR1 and SSTR2 in 27 pituitary adenomas using RT-PCR, including 2 and 3 ACTH-producing adenomas, respectively." (PMID 30627156, 2018). "Some other studies, however, have reported greater SSTR2 expression than SSTR3 or SSTR5 in SGAs and hormone-negative adenomas." (PMID 30020466, 2019). "In another study, 15 SCAs demonstrated greater immunoreactive scores for SSTR2 compared with null cell adenomas (defined in that study as hormone-, SF1-, and PIT1-negative samples; n = 10) and greater immunoreactive scores for SSTR5 compared with SGAs (n = 110)." (PMID 30020466, 2019). "SSTR5 expression was also lower in recurrent PIT-1-positive adenomas (p = 0.0350) but was higher in recurrent nonfunctioning adenomas (p = 0.0162) when compared to their specific primary subgroups." (PMID 30627156, 2018).
adenoma (continued). "SSTR2a and SSTR5 expression was variable and both cytoplasmic and membranous (scores 1 and 2), although none of the adenomas reached score 3 indicating circumferential membranous staining in more than 50 % of tumor cells." (PMID 27245663, 2016). "Immunoreactivity for SSTR2 and SSTR5 has been shown to be positive in 89% and 78% of silent thyrotroph adenomas, respectively, a difference that was not significantly different from the hormonally active adenomas." (PMID 30020466, 2019). "Furthermore, our thirty pituitary biopsy samples from patients undergoing surgery for CD with no adenoma detected during histopathological examination showed a significantly higher expression of SSTR2A and SSTR5." (PMID 30627156, 2018).
pituitary adenomas (21 papers, 2010 to 2025). "SSTR2 rs2236750 and SSTR5 rs34037914 genes’ single-nucleotide polymorphisms were analyzed to evaluate the associations with pituitary adenoma size." (PMID 39202532, 2024). "In pituitary adenomas, which secrete GH, this receptor was found to be prominently expressed, along with SSTR5 and SSTR2; interestingly, in the case of pituitary adenomas secreting ACTH, SSTR2 expression was not usually detected." (PMID 39329930, 2024). "SSTR2 and SSTR5 as primary SSTRs expressed in growth hormone secreting pituitary adenomas, are primary targets in somatostatin analogue therapy." (PMID 35053382, 2022). "Somatoprim, another second-generation SSA, is a multi-receptor targeting analog with a preference for SSTR2, SSTR4, and SSTR5, which was trialed in vitro on growth hormone (GH)-secreting pituitary adenomas." (PMID 33854479, 2021). "Previous reports of SSTR mRNA expression in GH-secreting pituitary adenomas in humans describe SSTR5 > SSTR2 whereas SSTR1 and SSTR3 expression can be highly variable and SSTR4 expression is absent." (PMID 30620005, 2019). "Two types of receptors are widely expressed at the surface of pituitary adenoma cells: the somatostatin receptor subtype 5 (SSTR-5) and the dopamine receptor subtype 2 (D2)." (PMID 25091295, 2014). "Therefore, this study aims to investigate the Ki-67 labeling index, SSTR2 rs2236750, SSTR5 rs34037914, and AIP rs267606574 polymorphisms, serum SSTR2, SSTR5, and AIP levels, and their association with the development of pituitary adenomas." (PMID 39202532, 2024). "It is used in the treatment of pituitary adenoma, where SSTR5 is more highly expressed than SSTR2." (PMID 39011594, 2024). "In clinical studies of patients with nonfunctioning pituitary adenoma, octreotide had little effect on tumor mass reduction but was associated with stabilization of postsurgical tumor remnants; in these patients, the SSTR5 subtype was the most abundant in the tumor, followed by SSTR3." (PMID 40255441, 2025). "Of the 5 SSTRs identified, SSTR2 and SSTR3 are expressed in most nonfunctioning pituitary adenoma samples, whereas SSTR5 is only expressed in a minority of tumors." (PMID 40255441, 2025). "SSTR2A, SSTR3, and SSTR5 are highly expressed in corticotroph pituitary adenomas and differ from nonadenomatous tissue, providing a promising target for medical treatment with somatostatin analogs." (PMID 30627156, 2018). "SSTR2A and SSTR5 were both expressed higher in nonadenomatous pituitary biopsies than in pituitary adenomas (p = 0.0126 and p = 0.0008, respectively)." (PMID 30627156, 2018). "While SSTR3 is expressed in most pituitary adenomas, independent of the functional type, SSTR5 and SSTR2 (SSTR5 more than SSTR2) are widely expressed in somatotroph, thyrotroph, corticotroph, lactotroph, and gonadotroph adenomas and are probably involved in the regulation of hormonal secretion." (PMID 32121432, 2020). "Paraffin-embedded tumor samples of 88 corticotroph pituitary adenomas and 30 nonadenomatous pituitary biopsies were analyzed after processing into tissue microarrays and immunohistochemical staining for SSTR 1, SSTR2A, SSTR3, SSTR4, and SSTR5." (PMID 30627156, 2018).
acromegaly (20 papers, 2016 to 2025). Acromegaly is an acquired disorder related to excessive production of growth hormone (GH) and characterized by progressive somatic disfigurement (mainly involving the face and extremities) and systemic manifestations. "Although previous literature suggests a favorable response to pasireotide in some patients with AIP mutations and acromegaly, pasireotide had only limited effect in our patient, possibly related to decreasing SSTR5 expression of the tumor." (PMID 35602875, 2022). "SST mutation has only been described in a single patient with acromegaly, in which there was a missense (Arg240Trp) variant in the SSTR5 gene." (PMID 30232095, 2018). "Pasireotide is approved clinically for the treatment of acromegaly displaying binding to multiple SSTR subtypes in order of SSTR5 > SSTR2 > SSTR3 > SSTR1." (PMID 38203605, 2023). "All other tumours causing acromegaly exhibited strong diffuse staining for SSTR2, with weaker but positive staining for SSTR5." (PMID 37851558, 2023). "All the eight tumours that caused acromegaly expressed SSTR2 and all but one tumour expressed SSTR5." (PMID 37851558, 2023). "Pasireotide resistance is possibly more related to SSTR2 expression than to SSTR5 in the general acromegaly population." (PMID 35602875, 2022). "Some authors suggested that the truncated somatostatin receptor 5 may modulate therapy and headache response in patients with acromegaly." (PMID 38244140, 2024). "Pasireotide has a 30- to 40-fold higher affinity for SSTR5 and lower affinity for SSTR2 compared with octreotide, which is why pasireotide has been attributed with potentially greater clinical efficacy in acromegaly than first-generation SSA." (PMID 38405148, 2024). "It is widely suggested that the response to SRLs treatment in acromegaly correlates with expression of the SSTR2 and SSTR5 subtypes." (PMID 31191457, 2019). "The expression of SSTR2 and SSTR5 was recently demonstrated in all the silent somatotroph adenomas reviewed (n = 21); however, expression of SSTR2 was significantly lower compared with the secreting counterpart, and SSTR5 expression was similar in both groups." (PMID 30020466, 2019). "Our aim was to evaluate the value of the immunohistochemical (IHC) scores of 2 subtypes, SSTR2 and SSTR5, in predicting the short-term efficacy of SSA therapy in patients with active acromegaly." (PMID 28396686, 2017). "The role of SSTR2 and SSTR5 heterodimerizations with enhanced response in acromegaly is further supported with observation describing the weak response of SST ligand in acromegaly with low SSTR2/SSTR5 ratio, as well as in the presence of the Sst5TMD4-truncated isoform of SSTR5." (PMID 38203605, 2023).
neuroendocrine tumors (18 papers, 2009 to 2026). "In the context of neuroendocrine tumors (NETs), somatostatin receptor subtype 5 (SSTR5) plays a crucial role, but understanding its regulatory mechanisms is still incomplete." (PMID 39202532, 2024). "177Lu-octreotate increases the activation of poly(ADP-ribose) polymerase-1 (PARP1), a DNA repair enzyme, after internalization in SSTR2-expressing and SSTR5 neuroendocrine tumor cells." (PMID 38140100, 2023). "They demonstrated that cases with low SSTR-2a combined with low SSTR-5 expressions and Ki-67 ≥2 had poor survival outcomes in neuroendocrine tumors." (PMID 26447992, 2015). "Despite SSTR5 having the highest level of the SSTR studied in terms of gene expression, staining of SSTR was low in myocardium samples in comparison with the neuroendocrine tumor positive control." (PMID 39038008, 2024). "177Lu-dotatate, known for its efficacy in treating somatostatin receptor-positive neuroendocrine tumors, could potentially target both NEPC tumors and the neuroendocrine component of AMPC19, as exemplified by the confirmed SSTR5 expression in our patient." (PMID 39349591, 2024). "In addition, it was found that PARPi led to enhanced cytotoxic effects of 177Lu-octreotate on both two-dimensional monolayer and three-dimensional spheroid models of neuroendocrine tumor cells expressing SSTR2 and SSTR5." (PMID 38140100, 2023). "Somatostatin analogues, such as octreotide, which display high binding affinity to SSTR2 and lower affinity to SSTR5 and SSTR3 (affinity rank order: SSTR2 > SSTR5 > SSTR3) are efficacious in the treatment of neuroendocrine tumors and exhibit only mild toxicity." (PMID 21985599, 2011). "While somatostatin can activate five somatostatin receptor subtypes (SSTR1-SSTR5), it has been shown that cyclic octapeptide octreotide selectively binds to the somatostatin subtype-2 (SSTR2) receptor (and, to a lesser extent, SSTR5), which is predominantly expressed in neuroendocrine tumours." (PMID 39451535, 2024).